SRGN (serglycin)
Description:
Plays a role in formation of mast cell secretory granules and mediates storage of various compounds in secretory vesicles. Required for storage of some proteases in both connective tissue and mucosal mast cells and for storage of granzyme B in T-lymphocytes. Plays a role in localizing neutrophil elastase in azurophil granules of neutrophils. Mediates processing of MMP2. Plays a role in cytotoxic cell granule-mediated apoptosis by forming a complex with granzyme B which is delivered to cells by perforin to induce apoptosis. Regulates the secretion of TNF and may also regulate protease secretion. Inhibits bone mineralization.
Synonyms: PRG; PRG1; PPG
Tractability: Antibody: UniProt places it where antibodies can reach, with high confidence; its Gene Ontology location is reachable by antibodies, with high confidence; UniProt predicts a signal peptide or a membrane-spanning region.
Gene: Protein-coding gene on chromosome 10 (69,088,103 to 69,104,811, forward strand). Ensembl gene ENSG00000122862.
Subcellular location: Cytoplasmic granule; Cytolytic granule; Secreted, extracellular space; Golgi apparatus
Subcellular location (Human Protein Atlas): Golgi apparatus; Predicted to be secreted
Pathways (Reactome):
Hemostasis: Platelet degranulation
Gene Ontology:
Molecular function: protein binding
Biological process: granzyme-mediated programmed cell death signaling pathway; negative regulation of bone mineralization; maintenance of granzyme B location in T cell secretory granule; maintenance of protease location in mast cell secretory granule; mast cell secretory granule organization; negative regulation of cytokine production; protein processing; secretory granule organization; T cell secretory granule organization
Cellular component: cytolytic granule; extracellular matrix; extracellular region; Golgi apparatus; mast cell granule; platelet alpha granule lumen; secretory granule
Genetic constraint (gnomAD): Loss-of-function variants: 3 observed, 9.56 expected, observed/expected ratio (o/e) 0.31, 90% interval 0.14 to 0.81. That is too few expected variants to judge how well the gene tolerates losing a copy. Missense variants: 166 observed, 196.8 expected, observed/expected ratio (o/e) 0.84, 90% interval 0.74 to 0.96. Synonymous variants: 57 observed, 73.98 expected, observed/expected ratio (o/e) 0.77, 90% interval 0.62 to 0.96.
Homologues: Orthologues: chimpanzee SRGN (97% identical), macaque SRGN (92% identical), dog SRGN (70% identical), rabbit SRGN (68% identical), pig SRGN (64% identical), guinea pig SRGN (61% identical), rat Srgn (51% identical), mouse Srgn (50% identical), zebrafish srgn (24% identical).
Diseases named in the same sentence as SRGN in open-access papers:
SRGN is named in the same sentence as 107 diseases in open-access papers, as found by Europe PMC text mining. Sharing a sentence is not in itself a finding about the gene and the disease. The quoted sentences say what the papers report.
breast carcinoma (42 papers, 2004 to 2025). "In breast cancer cell lines, serglycin expression is significantly associated with a mesenchymal phenotype." (PMID 35494005, 2022). "In both cohorts, SRGN is highest expressed in the basal-like subtype of breast cancer, a subtype associated with triple negative breast tumors and tumors with a mesenchymal phenotype." (PMID 35494005, 2022). "Here, we aimed to investigate the role of SRGN in chemoresistance of breast cancer and elucidate the underlying mechanisms." (PMID 32292495, 2020). "We therefore addressed the importance of serglycin for tumour growth and metastasis in an orthotopic and spontaneous tumour mouse model by introducing serglycin-deficiency into the MMTV-PyMT mammary carcinoma model, in which lung metastases develop." (PMID 27223472, 2016). "To elucidate why serglycin-deficient mice appeared to be protected from lung metastases we next analysed the primary mammary tumours." (PMID 27223472, 2016). "In breast cancer, serglycin has been demonstrated to be associated with chemotherapy resistance." (PMID 35494005, 2022). "A study in a murine mammary carcinoma model demonstrated that serglycin is essential for metastasis in lung, as serglycin-deficient cells present higher E-cadherin expression which is correlated to epithelial phenotype and cell–cell adhesion that attenuates cell migration." (PMID 32847060, 2020). "Previous researches have shown that the expression level of SRGN is up-regulated in many tumors, which contributes to tumor growth and metastasis, and is associated with poor prognosis, including acute myeloid leukemia, breast cancer, colorectal cancer, nasopharyngeal cancer." (PMID 34493692, 2021). "Increased SRGN expression has been observed in aggressive tumor cells, including glioblastoma, breast cancer, nasopharyngeal carcinoma, multiple myeloma, and lung cancer." (PMID 40542654, 2025). "In contrast to the promotional role of serglycin in cancer, recent results in breast cancer cells show low expression of the molecule compared to normal tissue." (PMID 40542654, 2025). "Co-culture of stromal fibroblasts with breast cancer cells results in elevated expression of SRGN and secretion of ADAMTS1 in fibroblasts and induced invasiveness of tumor cells." (PMID 38672477, 2024). "SRGN has been revealed to be highly expressed in multiple cancer types, including breast cancer, colon cancer, lung cancer and nasopharyngeal cancer." (PMID 38862740, 2024). "TNBC with increased SD on PrecontrastT1 showed a 23-fold, 13-fold, sevenfold, fivefold, and fivefold upregulation of CLEC3A, SRGN, HSPG2, KMT2D, and VMP1 respectively, and these genes are associated with poor survival in breast cancer." (PMID 37391754, 2023). "Mechanistically, SRGN can facilitate chemoresistance by cross-talking with the transcriptional coactivator YAP to maintain the stemness of breast cancer cells in vivo and in vitro." (PMID 37732314, 2023). "For instance, the upregulation of SRGN in chemoresistant breast cancer cells, serum and tissue samples from breast cancer patients with poor response to chemotherapy." (PMID 37732314, 2023). "Specifically, AGR3 promotes tamoxifen resistance in breast cancer, SRGN is a key molecule in mediating chemoresistance and stemness in breast cancer cells, and PPP1R1B is involved in resistance of breast cancer cells to trastuzumab." (PMID 37626402, 2023). "The overexpression of small molecular glycoprotein serglycin (SRGN) was found in multidrug-resistant breast cancer cells." (PMID 36968022, 2023). "Serglycin upregulates YAP expression in breast cancer cells by activating integrin α5/FAK/CREB signaling." (PMID 36693448, 2023). "To evaluate the association of serglycin expression with EMT in breast cancer, we started by examining RNA-Seq data from 48 breast cancer cell lines deposited to the Cancer Cell Line Encyclopedia." (PMID 35494005, 2022).
breast carcinoma (continued). "Here, we describe that SRGN expression in the basal-like subtype of breast cancer is correlated to the expression of genes involved in inflammatory response." (PMID 35494005, 2022). "SRGN expression was also found to be induced in the epithelial breast cancer cell line SK-BR-3 through induction of EMT by EGF, which demonstrates the strong association between serglycin and EMT, both in normal as well as in cancer cells." (PMID 35494005, 2022). "Using immunohistochemistry, serglycin was demonstrated to be present in breast cancer tissue, and serglycin was highly expressed in the aggressive MDA-MB-231 cell line." (PMID 35494005, 2022). "By examining immune staining and single cell sequencing data of breast cancer tissue, we show that serglycin is highly expressed by infiltrating immune cells in breast tumor tissue." (PMID 35494005, 2022). "Here, we have examined mRNA expression of serglycin in two breast cancer cohorts and a single cell sequencing data set, as well as the protein expression in a tumor microarray (TMA) by immunohistochemistry." (PMID 35494005, 2022). "Overexpression of serglycin in the breast cancer cell line MCF7 induced expression of mesenchymal markers fibronectin and vimentin and the EMT transcription factor Snail, accompanied with a change to a more mesenchymal like morphology." (PMID 35494005, 2022). "We further find that serglycin is more expressed by breast cancer cell lines with a mesenchymal phenotype as well as the basal-like subtype of breast cancers." (PMID 35494005, 2022). "Aggressive breast cancer cells with mesenchymal traits such as MDA-MB-231 and Hs578T, as well as basal-like breast tumors, express high levels of SRGN, in contrast to epithelial breast cancer cells and respective luminal subtypes of breast cancer." (PMID 35494005, 2022). "The observed high expression of serglycin in immune cells, and the association towards an immune response, prompted us to examine SRGN expression in a publicly available breast cancer single cell RNA-Seq data set." (PMID 35494005, 2022). "Increased expression of serglycin in epithelial breast cancer cells drives EMT, chemoresistance, proteolytic potential, invasion, and metastasis both in vitro and in vivo." (PMID 35494005, 2022). "Breast cancer single cell RNA-Seq data indicate that SRGN is highly expressed mostly in stromal cells and lymphocytes, including myeloid, dendritic, mast cells, T-lymphocytes, endothelial cells, and B-lymphocytes." (PMID 35494005, 2022). "Taken together, these data indicate that SRGN overexpression in chemoresistant breast cancer cells promotes chemoresistance and that SRGN level is negatively correlated with the prognosis of BC patients receiving chemotherapy." (PMID 32292495, 2020). "Many studies have confirmed that SRGN promotes tumor invasion and metastasis in colorectal cancer, non-small cell lung cancers, multiple myeloma, nasopharyngeal carcinoma, and breast cancer." (PMID 33262784, 2020). "In previous studies, most researches found that high SRGN expression was correlated with low survival rate of most tumors such as breast cancer, prostate cancer, colorectal cancer, nasopharyngeal carcinoma, glioma, and primary lung adenocarcinomas." (PMID 32370744, 2020). "The potential role of serglycin in metastatic dissemination has been investigated in a mouse model of breast cancer, where knockout of serglycin resulted in CTCs unable to establish metastatic tumors although not affecting primary tumor formation." (PMID 32984308, 2020). "We believe that novel therapeutic strategies for breast cancer can be designed by targeting the signaling mediated by the crosstalk between SRGN and YAP." (PMID 32292495, 2020). "The secretion of serglycin is also positively correlated with the aggressiveness of breast cancer cells." (PMID 30637950, 2019).
breast carcinoma (continued). "In this study, we investigated the expression and biological functions of SRGN gene in TNBC breast cancer cells and observed which signal pathways were affected." (PMID 28692037, 2017). "In a MMTV-PyMT-driven mouse model, genetic ablation of serglycin blocked lung metastasis of breast cancer." (PMID 28356139, 2017). "Emerging evidence suggests that elevated levels of serglycin can enhance breast cancer cell growth, migration, and invasion." (PMID 28356139, 2017). "SRGN has been demonstrated to induce proliferation, migration and invasion in breast cancer cells, but its expression in human breast cancer tissues and differential expression in different cell lines has not been reported." (PMID 28692037, 2017). "Although one study investigated the biological functions of SRGN in breast cancer cells by overexpression of serglycin, the affection of silencing SRGN gene expression on the proliferation, migration, and invasion of BC cells has not been reported." (PMID 28692037, 2017). "We therefore monitored SRGN mRNA expression using real-time PCR and measured protein expression by western blot in six breast cancer (BC) cell lines." (PMID 28692037, 2017). "Recent studies have shown overexpression of serglycin in several aggressive cancer types, including breast cancer, hepatocellular carcinoma, nasopharengeal carcinoma and myeloma." (PMID 28445977, 2017). "To investigate the role of serglycin proteoglycans in metastatic breast cancer we crossed PyMT+ and SG-/- mice." (PMID 27223472, 2016). "Taken together, our results suggest that serglycin is dispensable for primary tumour growth and functional vascularization of the primary tumour tissue in the PyMT mammary tumour model." (PMID 27223472, 2016). "In summary this is the first report on the role of serglycin in tumour progression using an immune competent spontaneous and orthotopic mammary tumour mouse model that develops lung metastases." (PMID 27223472, 2016). "To our knowledge this is the first study of serglycin in a spontaneous immune competent mammary tumour mouse model and we here report that expression of serglycin is essential for metastatic growth and dissemination." (PMID 27223472, 2016). "We went on to analyze the expression of serglycin in these breast cancer cell lines by qPCR and compare it to serglycin expression in cancer cell lines of different origin and tumorigenicity." (PMID 26581653, 2015). "We have previously investigated serglycin expression in breast cancer cell lines MDA-MB-231, MDA-MB-468, and MCF-7 of different aggressiveness by reverse transcription PCR." (PMID 26581653, 2015). "The same authors demonstrated that the overexpression of serglycin promotes breast cancer cell growth, migration, and invasion." (PMID 25140302, 2014). "In invasive MDA-MB-231 breast cancer cells serglycin represents the major PG type and is abundantly expressed and secreted in the culture medium." (PMID 24455486, 2014). "A similar mode of inhibition of the classical and lectin pathways was demonstrated for secreted serglycin by aggressive breast cancer cells." (PMID 24455486, 2014). "More importantly, aggressive breast cancer MDA-MB-231 cells constitutively secreted significant amounts of serglycin into the culture medium." (PMID 24205138, 2013). "Studies to investigate the prognostic importance of serglycin expression in breast cancer are in progress in our laboratory." (PMID 24205138, 2013). "To evaluate the migratory capacity of breast cancer cells over-expressing serglycin, we performed a wound healing assay." (PMID 24205138, 2013). "In this study, we show that serglycin is highly expressed in breast cancer tissues and by an aggressive breast cancer cell line." (PMID 24205138, 2013).
breast carcinoma (continued). "Total RNAs from MDA-MB-231 (high aggressive), MDA-MB-468 (medium aggressive) and MCF-7 (low aggressive) breast cancer cells cultured in serum-free medium or in complete culture medium were reverse transcribed and amplified using specific primers for serglycin." (PMID 24205138, 2013). "In conclusion, the data presented in this study demonstrated for the first time that serglycin is a major proteoglycan in breast cancer cells and is secreted into the culture medium, but also present in the cytoplasm in vesicles and at the plasma membrane." (PMID 24205138, 2013). "We found high expression levels for serglycin in cancer tissues and a correlation of higher expression of serglycin with tumor grade in breast cancer (manuscript in preparation)." (PMID 24205138, 2013). "We found that over-expression of intact serglycin slightly increased breast cancer cell growth after long term (96 h) culturing, as compared to mock-transfected (MCF-7V), or MCF-7 cells transfected with serglycin lacking GAG attachment sites (MCF-7VSG/−GAG)." (PMID 24205138, 2013). "Upregulation of serglycin only slightly affected breast cancer cell proliferation in cells grown on plastic surfaces." (PMID 24205138, 2013). "To confirm these data in our cell lines, we examined the expression of serglycin in breast cancer cell lines that clustered into three subgroups (MCF-7, MDA-MB-468 and MDA-MB-231 cells, clustered to Luminal, Basal A and Basal B, respectively)." (PMID 24205138, 2013). "Our data expand our knowledge on serglycin biology, showing that serglycin promotes breast cancer cell migration, invasion and anchorage-independent growth in a CS-dependent manner and inhibits complement system activity in the tumor microenvironment." (PMID 24205138, 2013). "We examined the role of serglycin in breast cancer cell proliferation, using MCF-7 cells stably over-expressing intact serglycin (MCF-VSG) and non-glycanated serglycin (MCF-7VSG/−GAG)." (PMID 24205138, 2013). "Here, we noticed a marked stimulation of anchorage-independent growth, migration and invasion of breast cancer cells over-expressing glycanated serglycin." (PMID 24205138, 2013). "In the present study, we show for the first time the in situ expression of serglycin by breast cancer cells by immunohistochemistry in patients’ material." (PMID 24205138, 2013). "Stable expression of serglycin in less aggressive MCF-7 breast cancer cells induced their proliferation, anchorage-independent growth, migration and invasion." (PMID 24205138, 2013). "The expression of serglycin in normal breast tissue and breast carcinoma was examined by immunohistochemistry in paraffin-embedded tissues." (PMID 24205138, 2013). "We demonstrated for the first time that serglycin is expressed both at mRNA and protein levels in breast cancer cells and we found increased expression of this PG in aggressive breast cancer cells." (PMID 24205138, 2013). "Although serglycin exhibited a moderate expression in normal mammary epithelial cells, it was found to be highly expressed in breast cancer cells in all tissues examined showing a strong cytoplasmic and cell-surface associated localization." (PMID 24205138, 2013). "For example, SRGN was shown to regulate TGF-β2 signaling in breast cancer, activate the NF-κB pathway in non-small lung cancer, participate in mitogen-activated protein kinase (MAPK)/β-catenin signaling in nasopharyngeal cancer and regulate the PI3K, Rac, and Src signaling pathways in breast cancer." (PMID 38167807, 2024). "In addition, YAP positively regulates serglycin expression to form a feed-forward circuit in breast cancer cells." (PMID 36693448, 2023). "Future studies should therefore investigate the molecular mechanisms behind this potential crosstalk, via serglycin, between the breast cancer cells and the infiltrating immune cells and if expression of serglycin by the immune cells can induce EMT in the breast cancer cells." (PMID 35494005, 2022).